KLHDC3 (kelch domain containing 3)
Description:
Substrate-recognition component of a Cul2-RING (CRL2) E3 ubiquitin-protein ligase complex of the DesCEND (destruction via C-end degrons) pathway, which recognizes a C-degron located at the extreme C terminus of target proteins, leading to their ubiquitination and degradation. The C-degron recognized by the DesCEND pathway is usually a motif of less than ten residues and can be present in full-length proteins, truncated proteins or proteolytically cleaved forms. The CRL2(KLHDC3) complex specifically recognizes proteins with a glycine (Gly) at the C-terminus, leading to their ubiquitination and degradation: recognizes the C-terminal -Arg-(Xaa)n-Arg-Gly, -Arg- (Xaa)n-Lys-Gly, and -Arg-(Xaa)n-Gln-Gly degrons. The CRL2(KLHDC3) complex mediates ubiquitination and degradation of truncated SELENOV and SEPHS2 selenoproteins produced by failed UGA/Sec decoding, which end with a glycine. May be involved in meiotic recombination process.
Synonyms: PEAS; hPeas; dJ20C7.3
Tractability: PROTAC: ubiquitination databases record sites on it.
Gene: Protein-coding gene on chromosome 6 (43,014,103 to 43,021,298, forward strand). Ensembl gene ENSG00000124702.
Subcellular location: Cytoplasm
Subcellular location (Human Protein Atlas): Nucleoplasm
Pathways (Reactome):
Cellular responses to stimuli: XBP1(S) activates chaperone genes
Gene Ontology:
Molecular function: chromatin binding; protein binding; ubiquitin-like ligase-substrate adaptor activity
Biological process: proteasome-mediated ubiquitin-dependent protein catabolic process; ubiquitin-dependent protein catabolic process via the C-end degron rule pathway; reciprocal meiotic recombination; protein ubiquitination
Cellular component: chromatin; Cul2-RING ubiquitin ligase complex; cytoplasm; nucleoplasm; cytosol
Genetic constraint (gnomAD): Loss-of-function variants: 4 observed, 35.77 expected, observed/expected ratio (o/e) 0.11, 90% interval 0.054 to 0.26. The upper end of that interval is the gene's LOEUF score, 0.26, which puts it in group 1 of 6, group 1 being the genes least tolerant of losing a copy. Missense variants: 225 observed, 483.22 expected, observed/expected ratio (o/e) 0.47, 90% interval 0.42 to 0.52. Synonymous variants: 155 observed, 183.56 expected, observed/expected ratio (o/e) 0.84, 90% interval 0.74 to 0.96.
Homologues: Orthologues: chimpanzee KLHDC3 (99% identical), macaque KLHDC3 (99% identical), rabbit KLHDC3 (98% identical), pig KLHDC3 (97% identical), guinea pig KLHDC3 (97% identical), rat Klhdc3 (97% identical), mouse Klhdc3 (97% identical), dog KLHDC3 (93% identical), tropical clawed frog klhdc3 (69% identical), zebrafish klhdc3 (46% identical). Paralogues in human: LZTR1 (27% identical), HCFC1 (26% identical), HCFC2 (25% identical), KLHDC2 (23% identical), KLHDC1 (21% identical), KLHDC10 (21% identical), RABEPK (18% identical), KLHDC4 (17% identical), FBXO42 (17% identical), KLHDC9 (16% identical).
Diseases named in the same sentence as KLHDC3 in open-access papers:
KLHDC3 is named in the same sentence as 5 diseases in open-access papers, as found by Europe PMC text mining. Sharing a sentence is not in itself a finding about the gene and the disease. The quoted sentences say what the papers report.
non-small cell lung carcinoma (1 paper, 2025). A group of at least three distinct histological types of lung cancer, including non-small cell squamous cell carcinoma, adenocarcinoma, and large cell carcinoma. "KLHDC3, a member of the kelch family, demonstrates heightened expression in non-small cell lung cancer, suggesting unfavorable patient outcomes." (PMID 40342975, 2025).
cancer (2 papers, 2019 to 2025). A tumor composed of atypical neoplastic, often pleomorphic cells that invade other tissues. "Cancer development was observed by the modulation of genes involved in cell death (HIST1H1T, CASP14, and DNAJC3), cancer related genes (WNT8A and CASC8), gene expression (transcription) (ZNF570 and ZFP42), and metabolism of proteins (CALB2 and KLHDC3)." (PMID 31797963, 2019). "Inhibiting KLHDC3 with peptides or small molecule inhibitors could offer a promising therapeutic strategy for cancers overexpressing KLHDC3, although no inhibitors currently exist." (PMID 39887712, 2025). "Like KLHDC3 and KLHDC4, the research conducted on the other family members indicates that targeting this subfamily could be a potential therapeutic strategy for various KLHDC‐overexpressing cancer types; however, potential inhibitors are not well documented." (PMID 39887712, 2025).
tumours (1 paper, 2025). "It has also been shown that KLHDC3 interacts with and contributes to the degradation of c‐Myc in tandem with Fbxw7, functioning in the regulation of cell growth and tumour formation." (PMID 39887712, 2025). "A CRISPR/Cas9 knockout of KLHDC3 significantly reduced lung cancer cell growth and suppressed tumour growth in‐vivo." (PMID 39887712, 2025). "KLHDC3 may also play roles in other types of tumours such as testicular and ovarian tumours." (PMID 39887712, 2025).
KLHDC3 also shares sentences with these, for which no sentence is quoted: Azoospermia (1 paper); hearing loss (1).